CRTAM (cytotoxic and regulatory T cell molecule)
Diseases named in the same sentence as CRTAM in open-access papers:
CRTAM is named in the same sentence as 33 diseases in open-access papers, as found by Europe PMC text mining. Sharing a sentence is not in itself a finding about the gene and the disease. The quoted sentences say what the papers report.
breast carcinoma (4 papers, 2013 to 2026). "Previous investigations have employed machine learning algorithms for molecular subtyping and prognostic model construction in breast cancer, identifying CRTAM, CLEC2D, and KLRB1 as pivotal hub genes associated with exhausted CD8+ T cell phenotypes." (PMID 40994935, 2025). "Unsupervised clustering performed on the filtered gene set and based on DNAM1, NCR3(NKp30), CD96 and Class I–Restricted T-cell–Associated Molecule (CRTAM) expression signatures was able to spontaneously segregate the breast cancer patients in two distinct cohorts." (PMID 23758773, 2013). "CRTAM also promotes antitumor immune response by enhanced CD8+ T-cell infiltration in breast cancer, which may correlate with the increased expression of MHC class I molecules." (PMID 41601635, 2026).
viral infection (4 papers, 2017 to 2024). "Early studies demonstrated that CRTAM-deficient mice could result in reduced protective immunity against viral infections in vivo." (PMID 36317112, 2022). "Compared to cluster 4, cluster 2 cells showed higher expression of SLAMF7, ZEB2, GZMB, GPR18, CD72, PDCD1 (PD1) and CRTAM that are known to be expressed in terminally differentiated effector cells in viral infections and various cancers." (PMID 38501302, 2024). "The authors confirmed that viral infection increases the frequency of CRTAM+ cells in the lung and that CRTAM knock-out mice exhibit decreased CD4 CTL activity during infection." (PMID 28167943, 2017). "Interestingly, CRTAM+ CD4 cells are found preferentially in the lung and intestinal lamina propria, the same tissues in which CD4 CTL are efficiently generated during viral infections in murine models (discussed further below)." (PMID 28167943, 2017).
COVID-19 (3 papers, 2021 to 2026). A disease caused by infection with severe acute respiratory syndrome coronavirus 2. "CRTAM was found to be downregulated in COVID-19 patients, and this gene regulates the activation and differentiation of several T-cell subsets, including NK cells." (PMID 41009536, 2025). "CRTAM was identified as a common gene among COVID-19 patients, regardless of their smoking history and diabetes status." (PMID 35003208, 2021). "CRTAM has been identified as a gene that is present in COVID-19 patients, regardless of their comorbidities." (PMID 35003208, 2021).
melanoma (3 papers, 2025 to 2026). A malignant, usually aggressive tumor composed of atypical, neoplastic melanocytes. "IFNγ signals were exclusively derived from NK‐cells and CD8+ T lymphocytes, whereas CRTAM signals were linked to both NK‐cells and melanoma cells." (PMID 41078003, 2025). "Since CD99 signaling can be initiated by other tumor components, in addition to melanoma cells (predicted to generate the strongest signals), we focused our analysis on CRTAM and IFNγ expression in NK‐cells." (PMID 41078003, 2025). "Focusing on the NK‐cell–melanoma interaction, we identified three primary regulatory mechanisms: IFNγ, a cytokine secreted by NK‐cells that plays a crucial role in modulating melanoma cell responses, as well as CD99 and CRTAM, two surface proteins involved in cell adhesion." (PMID 41078003, 2025).
intestinal infection (2 papers, 2019 to 2022). "CRTAM was found to enhance the degree of inflammation in intestinal infections, which suggested that CRTAM could be involved in the inflammatory immune response." (PMID 36317112, 2022). "Given our previous observation that CRTAM has a limited impact on the response to a non-pathogenic strain of T. gondii, we wanted to re-examine CRTAM function in the context of intestinal infection by the more pathogenic ME49 strain." (PMID 31312200, 2019).
parasitic infection (2 papers, 2019 to 2024). "We conclude that CRTAM enables an optimal Th17 host response to pathogenic parasitic infections that is required for controlling dysbiosis and bacterial translocation associated with infection." (PMID 31312200, 2019). "This hypothesis is supported by the finding that CRTAM protects against intestinal dysbiosis in parasitic infection by enabling the maturation of Th17 cells." (PMID 38931955, 2024).
rheumatoid arthritis (2 papers, 2024). A chronic, systemic autoimmune disorder characterized by inflammation in the synovial membranes and articular surfaces. "Furthermore, CRTAM was also confirmed as a potential hub gene involved in the development of rheumatoid arthritis (RA)." (PMID 38931955, 2024). "A study of rheumatoid arthritis single-cell RNA sequencing data demonstrated that five genes, KLRG1, CRTAM, SLAMF7, PTPN2, and KLRD1, were downregulated in activated and effector T cells isolated from synovial fluids." (PMID 38254179, 2024).
acute lymphoblastic leukemia (1 paper, 2022). Leukemia with an acute onset, characterized by the presence of lymphoblasts in the bone marrow and the peripheral blood. "The discovery of CRTAM+ NK cells in the bone marrow of patients with acute lymphoblastic leukemia may have potential immune response suppressive properties." (PMID 36317112, 2022).
allergic asthma (1 paper, 2014). A asthma with a basis in a pathological type I hypersensitivity reaction. "Furthermore, the percentage of CD177(+)CRTAM(+) neutrophils in peripheral blood was also elevated in patients with allergic asthma." (PMID 25221604, 2014).
aortic aneurysm (1 paper, 2022). A ruptured aneurysm located in the wall of the proximal portion of the descending aorta proceeding from the arch of the aorta. "CD8 CRTAM cells exhibited an escalating trend of proportions both in TAA and AAA than their corresponding control samples, whereas CD8 RUNX3 cells exhibited an opposite trend, namely, decreased proportions in aortic aneurysm compared with the normal group." (PMID 36703732, 2022).
atopic dermatitis (1 paper, 2024). "In addition, the CRTAM gene also plays a significant role in atopic dermatitis (AD), which is another immune disease sharing the pathophysiology cluster with IBD." (PMID 38931955, 2024).
autoimmune disease (1 paper, 2020). A disorder resulting from loss of function or tissue destruction of an organ or multiple organs, arising from humoral or cellular immune responses of the individual to their own tissue constituents. "CRTAM promotes the pro-inflammatory cytokine profile; therefore, it may take part in the immunopathology of autoimmune diseases such as diabetes type 1 or colitis." (PMID 33233764, 2020).
Autoimmunity (1 paper, 2023). The occurrence of an immune reaction against the organism's own cells or tissues. "Overview of dysregulated and dysfunctional DNAM-1, CRTAM, Tactile and TIGIT in autoimmunity and chronic inflammation." (PMID 36979144, 2023).
colitis (1 paper, 2020). Inflammation of the colon. "Recently, it was demonstrated that IFN-γ produced by CRTAM+ CD4 T cells plays a role in the inflammatory process observed in the DSS-induced colitis mouse model." (PMID 33233764, 2020).
diabetes type 1 (1 paper, 2020). "Moreover, after antigen-specific stimulation, a clear association between CRTAM expression and IFN-γ production in iNKT cells from healthy subjects and type 1 diabetes patients has been observed." (PMID 33233764, 2020).
diffuse large B-cell lymphoma (1 paper, 2022). "Another study reported that CRTAM was the most upregulated gene in responders to immunotherapy with diffuse large B-cell lymphoma." (PMID 35329826, 2022).
glioma (1 paper, 2013). A benign or malignant brain and spinal cord tumor that arises from glial cells (astrocytes, oligodendrocytes, ependymal cells). "In particular, the observation that in RBMECs the presence of glioma C6 CMinduced the expression of CRTAM, prompted us to explore in more detail the role of this adhesionmolecule in ReNcells CX transmigration." (PMID 23637756, 2013). "In RBMECs, glioma C6 CM did not affect the expression of occludinand claudins 1 and 5, but induced the expression of CRTAM." (PMID 23637756, 2013).
influenza (1 paper, 2023). An acute viral infection of the respiratory tract, occurring in isolated cases, in epidemics, or in pandemics; it is caused by serologically different strains of viruses (influenzaviruses) designated A, B, and C, has a 3-day incubation period, and usually lasts for 3 to 10 days. "In vivo, CRTAM-deficient mice show reduced protective immunity against influenza, due to a reduced migration of influenza-specific CD8+ CTLs and diminished cytotoxic function of CD4+ T cells." (PMID 36979144, 2023). "Herein, human viral antigen-responsive CD8+ T cells (i.e., influenza, CMV) selectively upregulate CRTAM as distinct marker, compared to control-stimulated CD8+ T cells." (PMID 36979144, 2023).
lung carcinoma (1 paper, 2026). "CRTAM–Necl-2 interactions promote cytotoxicity of NK cells and interferon-gamma secretion of CD8+ T cells in lung cancer, thus exerting the immunosurveillance role to distinguish tumors from normal cells." (PMID 41601635, 2026).
neuroblastoma (1 paper, 2021). Neuroblastoma (NB) is the most common solid, extracranial childhood tumor. "Together, the data suggest that the effector cells of high-risk neuroblastoma are CD4+ CD3+ NKG2C/E+ CRTAM+, namely CD4 CTLs." (PMID 33968044, 2021). "On the other hand, neuroblastoma cells expressed CADM1, the ligand of CRTAM." (PMID 33968044, 2021).
pan (1 paper, 2024). "Thus, we further investigated CRTAM's role in pan cancer since the ROC values of CRTAM displayed the highest score in both the training and test cohorts." (PMID 38385005, 2024).
prostate carcinoma (1 paper, 2012). A carcinoma that arises from epithelial cells of the prostate gland. "Of interest, our study found CRTAM significantly underexpressed in aggressive prostate cancer, suggesting a possible role for T-cell deficiency in prostate cancer." (PMID 23071848, 2012).
psoriasis (1 paper, 2023). An autoimmune condition characterized by red, well-delineated plaques with silvery scales that are usually on the extensor surfaces and scalp. "Although altered expression profiles of DNAM-1, CRTAM, Tactile and TIGIT are reported in peripheral blood samples of patients diagnosed with MS, RA, SSc, psoriasis, etc., a correlation with disease severity and progression in time is often lacking." (PMID 36979144, 2023).
tumor (21 papers, 2013 to 2026). "NK cell-mediated rejection of CADM1-expressing tumours is also influenced by the CRTAM gene in vivo, thus regulating the activation of various T-cell subtypes." (PMID 40759637, 2025). "(F) As in (E) where each cell is colored according to expression value of the genes CADM1 and CRTAM in tumor and non-tumor cells, respectively." (PMID 33155039, 2020). "TCS not only affects tumor cells directly, but also enhances anti-tumor immunity via regulating the expression and modulating the interaction of tumor suppressor TSLC1 and T cell-associated molecule CRTAM in the 3LL Lewis lung carcinoma tumor model." (PMID 30127254, 2018). "In another in vivo experiment, TCS elicits an anti-tumor immune response in a murine Lewis lung cancer model by boosting the interaction between tumor suppressor in lung cancer 1 (TSLC1) and class-I MHC-restricted T cell-associated molecule (CRTAM)." (PMID 23377374, 2013). "Another significant gene found as a DEG of the primary-site tumor in the HL_HPS group is CRTAM." (PMID 39339213, 2024). "Engagement of CRTAM promotes cytotoxic effects of NK cells towards Necl-2 expressing tumor cells." (PMID 24339981, 2013). "However, we speculate that in human patients CRTAM-dependent immune surveillance of CADM1 expressing tumours may provide an additional mechanism by which CADM1 suppresses tumour growth." (PMID 27035095, 2016). "These cells are associated with the inflammatory response and are implicated in multiple negatively regulated pathways that can facilitate the invasion and metastasis of tumor cells; in THn, CD38, NCF4, CRTAM, etc. are highly expressed." (PMID 39452125, 2024). "The secretion of IFN-γ and TNF induces tumor cell growth arrest as well as the expression of ligands for the activating NK cell receptors, DNAM-1 and CRTAM, which initiate NK cell tumor surveillance." (PMID 37111458, 2023). "Our results showed that the expression of the genes CD96, CD1d, CRTAM, LFA-1 and DNAM1, involved in the interaction of NK cells with target cells such as tumour cells or DCs, increased in patients with favourable prognosis." (PMID 23758773, 2013). "CD4+ T cells can acquire cytotoxic features under inflammatory and tumor conditions, including the secretion of granzymes, perforin, and IFN-γ, as well as the surface expression of killer ligands such as CRTAM, FasL, NKG2D, and TRAIL (CD253), which induce apoptosis in target cells." (PMID 41484912, 2026). "Three genes, CD8A, CRTAM, and EOMES, were consistently upregulated in all six tumor types." (PMID 38488909, 2024). "Our analysis reported that this mechanism of tumor suppression could be mediated by CADM1 and its receptor CRTAM." (PMID 33155039, 2020). "We observed that the expression of genes involved in NK crosstalk with DCs and tumour cells (DNAM1, CRTAM, CD96), promoting NK cell activation (NCR3(NKp30)) or modulating NKT activity (CD1d) was strongly and positively correlated with that of the 5 previously identified markers of good prognosis." (PMID 23758773, 2013). "We identity CD94, CD137(4-1BB), CD355 (CRTAM) as specific markers for antigen-specific activation of T-cells by autologous tumor cells, whereas other “check point” markers such as CTLA-4, PD-1, Tim3, CD39, CD103 were up-regulated by stimulation with unrelated tumor cells." (PMID 30400835, 2018).
infection (8 papers, 2017 to 2025). The state of being infected such as from the introduction of a foreign agent such as serum, vaccine, antigenic substance or organism. "Additionally, CRTAM was shown to be required to induce a robust Th17 response during an infection." (PMID 38931955, 2024). "Therefore, we posit that P12 mimics CRTAM to modulate the host immune system during infection." (PMID 39816809, 2023). "In our experimental model, at the peak of infection (14 dpi), the vast majority of splenic granzyme B+ and perforin+ CD4+ T cells expressed CRTAM." (PMID 40590226, 2025). "CRTAM+ cells traffic to mucosal and inflammation sites and mature into CD4+ cytotoxic T cells, aiding to protect against infection or induce inflammation." (PMID 38931955, 2024). "Nevertheless, there was a strong increase in the percentage of cells that expressed CRTAM, EOMES, and T-bet within the CD4+CD44hi T cells in HDAC1cKO-HDAC2HET mice, suggesting enhanced induction of CD4+ CTL features in HDAC1cKO-HDAC2HET Th cells upon infection." (PMID 32102981, 2020).
cancer (2 papers, 2024). A tumor composed of atypical neoplastic, often pleomorphic cells that invade other tissues. "Through pan cancer analysis, we found that CRTAM was more highly expressed and functioned as a hazardous factor of prognosis in GBM, LGG, KIPAN, UVM, and LAML." (PMID 38385005, 2024). "We also connected the potential impact of CRTAM in various cancers, which broadened researchers' understanding of RA and carcinoma." (PMID 38385005, 2024). "We thus hypothesized that consistently elevated expression of CRTAM in RA patients could increase the probability of several cancer types." (PMID 38385005, 2024). "These high correlation coefficients of CRTAM among cancers and RA tissues largely reminded us of that CRTAM could play a paradigmatic role in immune infiltration." (PMID 38385005, 2024). "Since several studies found that the consistent immune dysregulated state was not only involved in RA but also affected cancer patients, we further decided to link the relationship of CRTAM across cancers based on its high AUC value in both the training and testing cohorts." (PMID 38385005, 2024). "In addition, CRTAM might fuel cancer progression through immune signals, especially among RA patients." (PMID 38385005, 2024). "Moreover, CRTAM expression levels were strongly correlated with chemokine receptor, immune inhibitor, DC, CD8 Tcm cell, Tem cell, macrophage, and Treg cell levels across cancers, which was consistent with the enrichment analysis in this work." (PMID 38385005, 2024).
CRTAM also shares sentences with these, for which no sentence is quoted: asthma (1 paper); bacterial infections (1); diabetes (1); immune disease (1); metastatic tumors (1); oropharyngeal cancer (1); T-cell deficiency (1).